IL27 (interleukin 27)
Diseases named in the same sentence as IL27 in open-access papers (continued):
Sharing a sentence is not in itself a finding about the gene and the disease.
HIV-1 infection (continued). "This suggests that IL-27 is a potent anti-HIV-1 agent and that IL-27 therapy may therefore find utility in primary HIV-1 infection where highly potent treatments are predicted to be particularly useful." (PMID 23527130, 2013). "One way in which IL-27 may play a role in HIV-1 pathogenesis is in the increased levels of IL-10 noted in HIV-1 infection." (PMID 23527130, 2013). "By our calculations, if we assume a ∼65% reduction of HIV-1 replication with each cycle of HIV-1 infection with IL-27 treatment and an end result of ∼90% reduction in p24 after 14 days of treatment, we estimate that approximately three cycles of HIV-1 infection have taken place." (PMID 23527130, 2013). "Now that IL-27 has shown potent anti-HIV properties in three important cell types in HIV-1 infection (CD4+ T cell, macrophage and DC), the question remains whether this cytokine may be able to be utilized in the clinical setting." (PMID 23527130, 2013). "Overall, our data indicate that IL-27–induced autophagy may restrict HIV-1 infection in ABI-MAC." (PMID 34290273, 2021). "While IL-27 levels are not significantly altered in HIV-1 infection compared to uninfected controls there may be a small association between IL-27 and D-dimer levels and IL-27 and sCD163 levels." (PMID 24896094, 2014). "Finally, as IL-27 is part of the IL-12 family of cytokines, the other cytokines in this family (IL-12, IL-23 and IL-35) were assessed with regard to their possible role in inhibiting HIV-1 infection in DCs." (PMID 23527130, 2013). "IL-27 has long been considered a potent inhibitor of HIV-1 replication, a notion based on several reports showing that this cytokine controls HIV-1 infection in peripheral blood mononuclear cells (PBMCs), monocyte-derived macrophages, and dendritic cells." (PMID 36602368, 2023). "After HIV-1 virus infection, human AB serum+IL-27-treated MDMs restricted HIV-1 replication, and had accumulation of autophagosomes in MDMs, suggesting that IL-27-induced autophagy may restrict HIV-1 infection." (PMID 38566992, 2024). "We initially observed that neither HIV-1 infection nor IL-27 exposure modulated the expression of CD11a." (PMID 36602368, 2023). "Our findings illustrate the complexity of the HIV-1–host interactions and may impact the potential therapeutic use of IL-27 and other soluble mediators that induce BST-2/Tetherin expression for HIV-1 infection." (PMID 36602368, 2023). "Studies have shown that monocytes differentiate into macrophages after their activation by IL-27 and that macrophages are not sensitive to HIV-1 infection." (PMID 33390831, 2021). "As compared to IL-27, none of the other IL-12 family members were able to significantly inhibit HIV-1 infection." (PMID 23527130, 2013). "In the first of these studies, there was a small negative correlation between IL-27 levels and HIV-1 viral load, with the authors suggesting that HIV-1 infection may be down-regulating IL-27 to promote its pathogenesis." (PMID 24896094, 2014). "Our present results add new evidence that IL-27 does not function solely as an HIV-1 restriction factor and, instead, can also act to favor viral propagation, findings that may impact the perspectives of using this cytokine to treat HIV-1 infection." (PMID 36602368, 2023).
leishmaniasis (12 papers, 2012 to 2024). Infectious disease that is transmitted through the bite of hematophagous female phlebotomine sand flies. "IL-27 or IL-27 associated signaling molecules may be considered as exciting novel targets for immunomodulation in Leishmaniasis." (PMID 32849534, 2020). "On the other hand, IL-27 (P28/Ebi3), is acknowledged to have a dual function in inducing the immuno-pathology of Leishmaniasis." (PMID 39364404, 2024). "IL-27 is a regulatory cytokine in leishmaniasis due to its ability to exert pleiotropic effects on Th1, Th2 and Th17 functions." (PMID 33415318, 2020). "Severe lesions are reported in L. major-infected WSX-1−/− mice, which were associated with the appearance of the IL-17+ CD4+ cells, indicating a role for IL-27 in preventing the improper development of Th17 cells during Leishmaniasis." (PMID 32849534, 2020). "In both cutaneous and visceral forms of human Leishmaniasis, the IL-27 production is increased when the disease is in the active phase." (PMID 32849534, 2020). "Further, the clinical values of IL-27 as a marker of Leishmaniasis severity and/or as a monitoring marker of treatment efficacy need more considerations." (PMID 32849534, 2020). "In experimental models of leishmaniasis, the roles of IL-17A and IL-27 are still controversial: IL-17A, in synergy with IFN-γ, has been shown to potentiate leishmanicidal activities of infected macrophages." (PMID 27965662, 2016). "Previous reports on human leishmaniasis indicate that IL-27 increases when the disease is active in both cutaneous and visceral forms." (PMID 27867384, 2016). "Nevertheless, since IL-27 can directly regulate IL-17 responses, further study on its role in both experimental and human leishmaniasis is warranted." (PMID 23555256, 2013). "In the context of leishmaniasis, IL-27 exerts its function on T cells in a species-specific manner." (PMID 39639867, 2024). "IL-27 plays a complex role in the immuno-pathology of Leishmaniasis." (PMID 32849534, 2020). "IL-23 and IL-27 might play a role in human leishmaniasis and further studies are needed to understand the role of IL-23 and IL-27 in leishmaniasis." (PMID 23133467, 2012). "IL-27 induces CD4+ T cell-derived IL-10, which is canonical disease-enhancer in leishmaniasis, whilst at the same time it suppresses Th17/IL-17, both of which can promote disease progression when present." (PMID 33415318, 2020). "IL-27 was not able to suppress TNF-α production by cells from leishmaniasis patients: In addition to its role in stimulating a Th1-type immune response, IL-27 is known to attenuate inflammatory cytokine production." (PMID 24485388, 2014). "The L. major-infected macrophages from patients with healing forms of lesion produce a higher amount of IL-27 and IL-23 as compared with patients having non-healing forms of the lesion, suggesting that IL-27 and IL-23 may play synergistic roles with Th1 cytokines in protection against Leishmaniasis." (PMID 32849534, 2020).
lung carcinoma (12 papers, 2011 to 2022). "As for HCC, IL27R signaling within the tumor microenvironment restrained the cytotoxicity of innate cytotoxic lymphocytes, while in lung cancer, IL27 treatment increased sensitivity to cisplatin in A54916." (PMID 36713514, 2022). "IL-27 up-regulated HLA class I expression in the lung cancer cell lines analyzed and induced de novo expression in NB cells such as the SH-SY-5Y cell line." (PMID 27683036, 2016). "Recent findings indicated that IL-27 suppresses the expression of stem cell and mesenchymal transition genes in lung cancer cells." (PMID 27683036, 2016). "Previous studies assessing IL-27's effects in lung cancer have used mouse autograft models or, in vitro experiments with both murine and human lung AC cell lines." (PMID 25638163, 2015). "Our data confirm, in pre-clinical xenograft models of human lung AC and SCC, the anti-lung cancer effects of IL-27." (PMID 25638163, 2015). "Overall, our findings support that STAT1, but not STAT3, plays a primary role in inhibition of pro-angiogenic factor production in human lung cancer by IL-27 treatment." (PMID 24274066, 2013). "This study showed that IL-27 treatment in lung cancer cells led to increased E-cadherin expression and decreased expression of vimentin and Snail with inhibition of cell migration by suppression of cyclooxygenase-2-mediated activities." (PMID 24274066, 2013). "Although a study showed that either over-expression or treatment with recombinant IL-27 led to anti-tumor activity on murine and human lung cancer cells, there is limited insight on the mechanism that modulates EMT and angiogenesis." (PMID 24274066, 2013). "In this study, we examined the production of pro-angiogenic factors, VEGF, IL-8/CXCL8, and CXCL5, to determine the effects of IL-27 on angiogenesis in human lung cancer." (PMID 24274066, 2013). "In this study, the gene of interleukin-27 (IL-27), a novel IL-6/IL-12 family cytokine, was transfected in LL/2 (Lewis lung cancer cell) by using a cationic liposome." (PMID 24198814, 2013). "Our results revealed that IL-27-treated lung cancer cells show increased epithelial marker (E-cadherin and γ-catenin), decreased Snail (transcriptional repressor of E-cadherin), and decreased mesenchymal marker (N-cadherin and vimentin) expression." (PMID 24274066, 2013). "In lung carcinoma, IL27 down-regulates vimentin expression and reduces cellular migration and invasion." (PMID 21559505, 2011). "Furthermore, by means of molecular biology and immunohistochemical studies, we have assessed IL-27Receptor(R) expression in lung cancer samples and analyzed the rationale for a future IL-27 application in the clinical setting of NSCLC." (PMID 25638163, 2015). "To determine whether lung cancer patients could benefit from IL-27's antitumor effects, we next immunohistochemically evaluated the expression and distribution of IL-27R in AC and SCC tissue sections." (PMID 25638163, 2015). "Taken together, these results indicate that IL-27 production was negatively correlated with the commitment of Th17 cells and might have a therapeutic potential in lung cancer." (PMID 25969628, 2015). "Our data, drawn from patient samples, suggest that IL-27 may be used to overcome this drawback and be of particular benefit in advanced lung cancer stages." (PMID 25638163, 2015). "For example, IL-27 could also induce indoleamine 2,3-dioxygenase (IDO) and PD-L1 expression on monocytes and tumor-associated macrophages and on human prostate, breast and lung cancer cells." (PMID 33418929, 2021). "Majumder proposed that IL-28B alone or in combination with IL-27 can decrease lung nodules number and increase the activity of CD8+ cells in lung cancer bearing mice." (PMID 34818327, 2021). "IL27 was reported to drastically enhance the efficacy of immunotherapy without no significant side effects in mouse models of lung cancer." (PMID 34733272, 2021).
lung carcinoma (continued). "In addition, IL-27 directly suppresses tumorigenicity through downregulation of vimentin, COX-2, and PGE2 on lung cancer cells." (PMID 25969628, 2015). "In addition, IL-27 induced IDO or PD-L1 expression in monocytes and in human PC3 prostate and A549 lung cancer cells." (PMID 26657115, 2015). "Since AC and SCC are the most common histotypes of lung cancers, ~85% of NSCLC, we looked to see whether IL-27 acts as an antitumor agent in these forms." (PMID 25638163, 2015). "Thus, the importance of JAK signal transduction in the ability of IL-27 to activate the STAT1 and STAT3 pathways in human lung cancer was studied." (PMID 24274066, 2013). "IL-27 has been shown to have non-immune antitumor effects in lung cancer that include suppression of COX-2 and PGE2, reduction of vimentin levels, and inhibition of cell migration and invasion." (PMID 24274066, 2013). "Interestingly, the inhibition of STAT1 activation led to increased STAT3 activation in IL-27 treated lung cancer cells whereas inhibition of STAT3 activation alone did not significantly impact STAT1 expression." (PMID 24274066, 2013).
non-small cell lung carcinoma (12 papers, 2013 to 2024). A group of at least three distinct histological types of lung cancer, including non-small cell squamous cell carcinoma, adenocarcinoma, and large cell carcinoma. "Sera and bronchoalveolar lavage fluid (BALF) taken prior to chemotherapy from patients diagnosed with non-small cell lung cancer (NSCLC) were analyzed by enzyme linked immunosorbent assay (ELISA) to assess circulating levels of IL-27, IL-29, IL-31, and IL-33." (PMID 30205617, 2018). "In non-small cell lung cancer patients, IL-27 promoted the anti-tumor function of myeloid cells and suppressed epithelial-to-mesenchymal transition (EMT) in cancer cells." (PMID 33418929, 2021). "Another study also claimed that IL-27 inhibited in vitro cell migration of non-small cell lung cancer, accompanied by elevated expression of epithelial markers." (PMID 28746469, 2017). "We then asked whether IL-27 could up-regulate HLA class I expression also on other human cancer cells including three non-small cell lung cancer (NSCLC) and three human neuroblastoma (NB) cell lines." (PMID 27683036, 2016). "Kachroo demonstrated that IL-27 attenuated EMT and the production of pro-angiogenic factors in a STAT1-dominant pathway in human non-small cell lung cancer." (PMID 26932661, 2016). "More recently, IL-27 was shown to down-regulate stemness- and EMT-related genes in non-small cell lung cancer cells and to trigger myeloid cell anti-tumor activities in xenotransplant tumor models." (PMID 26657115, 2015). "In this study, we investigated the role of IL-27 in regulating EMT and angiogenesis through modulation of the STAT pathways in human non-small cell lung carcinoma (NSCLC) cells." (PMID 24274066, 2013).
Behcet disease (11 papers, 2011 to 2025). A chronic, relapsing, multisystemic vasculitis characterized by mucocutaneous lesions, as well as articular, vascular, ocular and central nervous system manifestations. "Upon stimulation with recombinant (r)IL-37, DCs from patients with Behcet’s disease (BD) have decreased IL-6 and IL-1β expression, and increased IL-27 expression." (PMID 29137646, 2017). "In the present study, we provide evidence that decreased expression of IL-27 may be involved in the pathogenesis of Behçet’s disease." (PMID 24887071, 2014).
colon carcinoma (11 papers, 2013 to 2024). "Then, they observed that an FFAR2 agonist reduced the number of colon tumors, and decreased the frequency of IL27 + DCs in tumors of ApcMin/+/DSS mice." (PMID 39432182, 2024). "In a quite similar way as described for IL-12, overexpression of IL-27 in colon cancer cells was able to trigger local IFNγ secretion, NK cell-mediated antitumor effects, and T cell-mediated tumor-specific cytotoxicity." (PMID 36428508, 2022). "Combinatorytreatment using cytokines and RAS-targeted therapy resulted insynergistic tumor inhibition, as seen in pancreatic cancer usingInterferon-alpha (IFN-α) and in colon cancer, with Interleukin-27 (IL-27)." (PMID 36206378, 2022). "Murine IL-30 has been shown to suppress the anti-tumor effects of IL-27, and to reduce the survival of colon cancer-bearing mice." (PMID 32143355, 2020). "Originally identified as the p28 subunit of the heterodimeric cytokine Interleukin(IL)-27, and found to suppress the antitumor effects of IL-27 in colon cancer, IL-30 is emerging as a new and intriguing factor that may condition PC onset and progression." (PMID 31366386, 2019). "In contrast to the beneficial effects of IL-12 and IL-27 on the immune system-mediated control of CRC development, IL-23 was found to promote the immune evasion of colon tumor cells." (PMID 36428508, 2022).
neuroblastoma (11 papers, 2011 to 2022). Neuroblastoma (NB) is the most common solid, extracranial childhood tumor. "The same seems to be true in cases of esophageal and prostate carcinomas and neuroblastomas, and according to published studies IL-27 shows antitumor activity in these neoplasms." (PMID 30581461, 2018). "For example, mouse TBJ neuroblastoma or C26 colon carcinoma cells, genetically engineered to express a single-chain IL-27 molecule, lost their tumorigenic potential when implanted in syngeneic mice." (PMID 28255204, 2017). "Local delivery of IL-27 to tumors significantly decreased metastasis and growth of neuroblastoma and CT26 tumors by inducing tumor specific CTL51–53." (PMID 29021521, 2017). "We found that IL-27 enhanced HLA class-I molecule levels in different types of human cancer cells, including neuroblastoma tumor cells, which showed very low constitutive expression." (PMID 28255204, 2017). "In the same year, results from TBJ murine neuroblastoma tumors also demonstrated that IL-27 has a potent ability to induce tumor-specific antitumor and protective immunity." (PMID 26014498, 2015). "In the TBJ neuroblastoma model, the effect of transduced IL-27 could be further enhanced by the administration of IL-2, which led to the complete regression of neuroblastoma metastases." (PMID 28255204, 2017). "Our present work shows that also IL-27 may correct this defect in cancer cells showing low-HLA class I expression, such as the A2780 ovarian cancer cell line or human neuroblastoma cells." (PMID 27683036, 2016). "The cytokines IFN-γ, IL-2, IL-7, IL-12, IL-15, IL-18, IL-21, and IL-27, promoted neuroblastoma regression via enhancing the efficacy of effector cells, whereas VEGF, IL-6, and IL-10 induced neuroblastoma progression through their immunosuppressive activities." (PMID 33322408, 2020). "An early report showed that murine neuroblastoma cells engineered to express IL-27 showed delayed tumor formation in syngeneic mice and showed increased MHC class I in the tumor environment due to indirect, IFN-γ-mediated, or possibly direct effects of IL-27." (PMID 27683036, 2016). "IL27 also inhibits metastasis in the B16F10 and neuroblastoma TBJ tumor models." (PMID 21559505, 2011). "IL-27 has been reported to induce the expression of MHC class-I molecules, a typical effect of IFNs, in different cell types including mouse naïve CD4+ T cells, neuroblastoma cells, human monocytic cell lines, endothelial cells, hepatocytes, hepatoma cell lines, and hepatic stellate cells." (PMID 28255204, 2017).